GALNT2 (polypeptide N-acetylgalactosaminyltransferase 2)
Diseases named in the same sentence as GALNT2 in open-access papers (continued):
Sharing a sentence is not in itself a finding about the gene and the disease.
neurodevelopmental disorder (2 papers, 2022 to 2025). A behavioral and cognitive disorder with onset during the developmental period that involves impaired or aberrant development of intellectual, motor, or social functions. "Biallelic loss of function mutations in GALNT2 [MIM 602274] cause a neurodevelopmental disorder of O-linked glycosylation [MIM: 618885]." (PMID 36413568, 2022).
infection (1 paper, 2024). The state of being infected such as from the introduction of a foreign agent such as serum, vaccine, antigenic substance or organism. "Early in infection, we observed some differences in the trafficking of EBOV GP—lower and enhanced GP colocalization with lysosomal marker LAMP1 was seen in GALNT2 KO and GALNT3 KO cells, respectively." (PMID 38757972, 2024).
retinopathy (1 paper, 2024). "A variant of the GALNT2-gene (rs4846913), previously linked to lower apo-CIII0a, was associated with a decreased prevalence of retinopathy (OR = 0.739, 95% CI 0.575 to 0.951)." (PMID 38791405, 2024). "The genetic variant rs4846913-A located in the GALNT2 gene, previously associated with decreased apo-CIIIoa, was found to be negatively associated with prevalent retinopathy in Model 2 in the DiaGene study (OR = 0.739, 95% CI 0.575 to 0.951)." (PMID 38791405, 2024). "Replication in a larger cohort is needed to confirm whether increased activity of GALNT2 reduces the risk of retinopathy through glycosylation of apo-CIII." (PMID 38791405, 2024). "In addition, a genetic variant in the GALNT2-gene, previously linked to increased glycosylation of apo-CIII, was found to be negatively associated with retinopathy." (PMID 38791405, 2024). "Moreover, a variant in the GALNT2-gene was associated with apo-CIII glycosylation and retinopathy, suggesting a causal effect." (PMID 38791405, 2024).
GALNT2 also shares sentences with these, for which no sentence is quoted: metabolic disease (5 papers); epilepsy (3); cardiovascular diseases (2); Gestational Diabetes Mellitus (2); adenosquamous carcinoma (1); angina (1); atherosclerosis (1); breast carcinoma (1); cervical (1); chronic myeloid leukemia (1); colon adenocarcinoma (1); dementia (1); endometrioid adenocarcinoma (1); exocrine pancreatic insufficiency (1); gynecologic cancer (1); head-neck squamous cell carcinoma (1); hypercholesterolemia (1); hypertriglyceridaemia (1); insomnia (1); ischemic stroke (1); lung squamous cell carcinoma (1); metastasis (1); mucinous adenocarcinoma (1); oral cancer (1); Parkinson disease (1); polycystic ovary syndrome (1); prostate carcinoma (1); schizophrenia (1); Sepsis (1); squamous cell carcinoma (1).
A further 2 diseases each share a sentence with GALNT2 in 1 paper.